SLC28A1 (solute carrier family 28 member 1)
Description:
Sodium and pyrimidine nucleoside symporter of the plasma membrane that imports uridine, thymidine and cytidine into cells by coupling their transport to the transmembrane sodium electrochemical gradient. Also transports adenosine, an atypical substrate transported with high apparent affinity, but low maximum velocity. Therefore, exhibits the transport characteristics of the nucleoside transport system cit or N2 subtype (N2/cit). Involved in renal nucleoside (re)absorption.
Synonyms: hCNT1; CNT1; URCTU
Tractability: Antibody: UniProt places it where antibodies can reach, with high confidence; its Gene Ontology location is reachable by antibodies, with high confidence; UniProt predicts a signal peptide or a membrane-spanning region. PROTAC: its protein half-life has been measured; a small molecule that binds it is known.
Target class: Transporter; SLC28 Na+-coupled nucleoside transport family; Electrochemical transporter; SLC28 and SLC29 families of nucleoside transporters; SLC superfamily of solute carriers
Safety:
Unwanted effects reported when the protein is acted on. In parentheses: how it was acted on, where the effect was seen, and who reports it.
cardiotoxicity (source: ClinPGx)
hematologic toxicity (source: ClinPGx)
neutropenia (source: ClinPGx)
Gene: Protein-coding gene on chromosome 15 (84,884,612 to 84,945,803, forward strand). Ensembl gene ENSG00000156222.
Subcellular location: Cell membrane; Apical cell membrane
Subcellular location (Human Protein Atlas): Plasma membrane; Cytosol; Nuclear speckles
Pathways (Reactome):
Transport of small molecules: Transport of nucleosides and free purine and pyrimidine bases across the plasma membrane
Gene Ontology:
Molecular function: azole transmembrane transporter activity; pyrimidine- and adenosine-specific:sodium symporter activity; uridine transmembrane transporter activity; cytidine transmembrane transporter activity; nucleoside:sodium symporter activity; purine nucleobase transmembrane transporter activity; nucleoside transmembrane transporter activity
Biological process: azole transmembrane transport; cytidine transport; nucleoside import across plasma membrane; nucleoside transmembrane transport; pyrimidine-containing compound transmembrane transport; uridine transmembrane transport; purine nucleobase transmembrane transport; pyrimidine nucleobase transport
Cellular component: apical plasma membrane; plasma membrane; brush border membrane; membrane
Genetic constraint (gnomAD): Loss-of-function variants: 61 observed, 72.17 expected, observed/expected ratio (o/e) 0.85, 90% interval 0.69 to 1.05. The upper end of that interval is the gene's LOEUF score, 1.05, which puts it in group 4 of 6, group 1 being the genes least tolerant of losing a copy. Missense variants: 828 observed, 846.63 expected, observed/expected ratio (o/e) 0.98, 90% interval 0.92 to 1.04. Synonymous variants: 359 observed, 342.97 expected, observed/expected ratio (o/e) 1.05, 90% interval 0.96 to 1.14.
Homologues: Orthologues: chimpanzee SLC28A1 (99% identical), macaque SLC28A1 (95% identical), pig SLC28A1 (86% identical), mouse Slc28a1 (84% identical), rat Slc28a1 (82% identical), guinea pig SLC28A1 (76% identical), rabbit SLC28A1 (71% identical), tropical clawed frog slc28a2 (57% identical), zebrafish slc28a1 (50% identical), Drosophila melanogaster CNT2 (31% identical), Drosophila melanogaster CNT1 (29% identical), Caenorhabditis elegans slc-28.2 (25% identical), and 1 more. Paralogues in human: SLC28A2 (63% identical), SLC28A3 (44% identical).
Diseases named in the same sentence as SLC28A1 in open-access papers:
SLC28A1 is named in the same sentence as 36 diseases in open-access papers, as found by Europe PMC text mining. Sharing a sentence is not in itself a finding about the gene and the disease. The quoted sentences say what the papers report.
pancreatic cancer (15 papers, 2010 to 2023). "Study found that a high expression of SLC28A1 (Solute Carrier Family 28 Member 1) was significantly associated with poor overall survival in pancreatic cancer patients." (PMID 36185201, 2022). "Both Slc28a1+/+ and Slc28a1−/− vehicle control mice developed large pancreatic tumors at 25 days post implantation." (PMID 37264059, 2023). "In pancreatic cancer, SLC28A1 was down-regulated when compared with non-neoplastic tissues, and high tumor transcript levels of SLC28A1 predicted a poor OS in pancreatic ductal adenocarcinomas patients." (PMID 35053305, 2022).
leukemia (4 papers, 2016 to 2024). A malignant (clonal) hematologic disorder, involving hematopoietic stem cells and characterized by the presence of primitive or atypical myeloid or lymphoid cells in the bone marrow and the blood. "Thus, the SLC28A1 intronic variant c.795+4320T>A (rs11853372) has been associated with low-intracellular cytarabine levels in cancer cells collected from children with leukemia." (PMID 39143954, 2024). "This was supported by increased AZA sensitivity of canine kidney and leukemia cell lines transfected with SLC28A1 compared to cells lines transfected with SLC29A1, SLC29A2, and SLC28A2." (PMID 36834962, 2023). "In line with the present findings, SLC28A1, SLC28A2, and SLC28A3 were poorly expressed in primary bone marrow blasts and leukemia cell lines." (PMID 36834962, 2023). "The mRNA amounts of the main nucleoside transporters (NT) and intracellular metabolizing enzymes (ME), hENT1, hENT2 (SLC29A2), hCNT1 (SLC28A1), hCNT2 (SLC28A2), hCNT3 (SLC28A3), DCK and cN-II (NT5C2), were measured in 50 pediatric leukemia cases by RQ-PCR." (PMID 27391351, 2016).
breast carcinoma (3 papers, 2017 to 2018). "Interestingly, several variants in SLC28A1 have been associated with different outcomes in non-small cell lung cancer and breast cancer when treated with gemcitabine, suggesting that variant differences across the populations may be involved." (PMID 29273096, 2017).
non-small cell lung carcinoma (3 papers, 2017 to 2024). A group of at least three distinct histological types of lung cancer, including non-small cell squamous cell carcinoma, adenocarcinoma, and large cell carcinoma. "In patients with non-small cell lung cancer (NSCLC) treated with gemcitabine-based therapy, the non-synonymous SLC28A1 variant c.1561G>A/T (p.Asp521Asn/Tyr, rs2242046) has been associated with increased myelotoxicity due to an increased gemcitabine absorption." (PMID 39143954, 2024).
diabetes (2 papers, 2020 to 2023). "The present study showed that a variant associated with the high end of the z-insulin spectrum (rs2122859) was located on the SLC28A1 gene, which has been shown to be associated with both diabetes and late-onset Alzheimer’s disease." (PMID 37420130, 2023). "On the other hand, SLC28A1, a high-affinity pyrimidine nucleoside transporter, plays a role in renal reabsorption and has been observed to be impaired during diabetes." (PMID 34968291, 2020).
pancreatic adenocarcinoma (2 papers, 2015 to 2021). "To ascertain the possible cause of the diminished expression of hCNT1 in cancer, we looked for the presence of mutations and alterations in methylation in the SLC28A1 gene by analyzing data from the TCGA-COAD (colon adenocarcinoma) and TCGA-PAAD (pancreatic adenocarcinoma) projects." (PMID 34647142, 2021).
atrial fibrillation (1 paper, 2020). A disorder characterized by an electrocardiographic finding of a supraventricular arrhythmia characterized by the replacement of consistent P waves by rapid oscillations or fibrillatory waves that vary in size, shape and timing and are accompanied by an irregular ventricular response. "The Slc28a1 gene stands out as the protein-coding gene for Solute Carrier Family 28 Member 1, and has been related to some pathologies such as cancer, atrial fibrillation, and antiretroviral therapy absorption, but not to epilepsy." (PMID 32528245, 2020).
kidney cancer (1 paper, 2020). Primary or metastatic malignant neoplasm involving the kidney. "For example, CNT1 (SLC28A1) is high in the kidneys, liver, and small intestine and, accordingly, highly expressed in kidney cancers." (PMID 33020720, 2020).
lung carcinoma (1 paper, 2023). "CDA + 435, and SLC28A1 + 1561 are worthy of further investigation as potential indicators of patient outcome after gemcitabine treatment in lung cancer." (PMID 37150853, 2023).
type 2 diabetes (1 paper, 2023). "For instance, a variant associated with the 85th percentile of z-insulin was located on the SLC28A1 (or CNT1) gene that has been linked to type 2 diabetes." (PMID 37420130, 2023).
cancer (14 papers, 2006 to 2024). A tumor composed of atypical neoplastic, often pleomorphic cells that invade other tissues. "Differential analysis on cancer reads of the KIRC against the other 8 PDX types revealed 1,181 DE genes (q< 0.05, BH adjusted), with the lowest q-value identified for POU3F3, SLC28A1, and CDH6 genes." (PMID 35079698, 2021). "The uptake of 5-FU by cancer cells is mainly carried out through the concentrative nucleoside transporter 1 (CNT1, SLC28A1), whose expression is downregulated in HB." (PMID 30909445, 2019).
tumor (14 papers, 2015 to 2024). "The expression of some genes in PDAC tumor tissue, including SLC28A1 and SLC29A1, has been associated with gemcitabine response." (PMID 35740571, 2022). "Expression of SLC28A1 and SLC29A1 in PDAC tumor tissue have been best studied and are associated with gemcitabine response." (PMID 30477242, 2018). "There was a minor, but significant, decrease in the total tumor burden in Slc28a1−/− mice receiving vehicle compared to the control receiving vehicle, suggesting that CNT1 KO environment affected tumor burden in a tumor cell nonautonomous manner." (PMID 37264059, 2023). "While both Slc28a1+/+ and Slc28a1−/− dFdC-treated mice exhibited reduced tumor growth over time, only Slc28a1+/+ mice and not Slc28a1−/−mice responded effectively to dFdC treatment." (PMID 37264059, 2023).
infection (4 papers, 2014 to 2025). The state of being infected such as from the introduction of a foreign agent such as serum, vaccine, antigenic substance or organism. "Lower transcription levels of NUDT14, KLK10, SLC28A1, SMAD4 and SEPT7 during a series of stages of infection may reflect the inabilities of these genes to participate in glucose metabolism, tumorigenesis, nucleoside biosynthesis and transport, signaling and microtubule stabilization respectively." (PMID 25903558, 2015).
SLC28A1 also shares sentences with these, for which no sentence is quoted: ovarian carcinoma (2 papers); pancreatic ductal adenocarcinoma (2); acute myeloid leukemia (1); Alzheimer disease (1); anemia (1); bladder cancer (1); breast tumors (1); cholangiocarcinoma (1); colon adenocarcinoma (1); colorectal carcinoma (1); cyst (1); epilepsy (1); glioma (1); gynecologic tumors (1); gynecological cancer (1); hepatocellular carcinoma (1); kidney tumors (1); liver cancer (1); nephrotic syndrome (1); neutropenia (1); renal diseases (1); schizophrenia (1); uridine-cytidineuria (1).